TWIST2 (twist family bHLH transcription factor 2)
Diseases named in the same sentence as TWIST2 in open-access papers (continued):
Sharing a sentence is not in itself a finding about the gene and the disease.
focal facial dermal dysplasia (2 papers, 2017 to 2023). Focal facial dermal dysplasias (FFDD) are rare ectodermal dysplasias, characterized by congenital bitemporal (resembling forceps marks) or preauricular scar-like lesions associated with additional facial and or systematic manifestations. "A later study by the same group identified germline nonsense homozygous mutations in the TWIST2 gene in patients with autosomal recessive Setleis syndrome, an inherited developmental disorder under the branch of Focal Facial Dermal Dysplasia (FFDD)." (PMID 37600794, 2023).
head and neck squamous cell carcinoma (2 papers, 2011 to 2017). A squamous cell carcinoma that arises from any of the following anatomic sites: lip and oral cavity, nasal cavity, paranasal sinuses, pharynx, larynx, and salivary glands. "Here, we study the prognostic significance of TWIST1 and TWIST2 in Head and Neck squamous cell carcinoma (HNSCC) as well as interactions of TWISTs with both gender and smoking in patient survival." (PMID 29156759, 2017).
Hepatic steatosis (2 papers, 2021 to 2022). Steatosis is a term used to denote lipid accumulation within hepatocytes. "Another study showed that KLF15 can activate twist-related protein 2 (TWIST2) to ameliorate liver steatosis and inflammation by modulating nuclear factor (NF)-κB or sterol regulatory element-binding protein 1c (SREBP1c)-fibroblast growth factor 21 (FGF21) signaling pathways." (PMID 34299189, 2021).
Insulin resistance (2 papers, 2019 to 2021). Increased resistance towards insulin, that is, diminished effectiveness of insulin in reducing blood glucose levels. "The distribution pattern of TWIST1 and TWIST2 seems to be different; the levels of TWIST1 are higher in subcutaneous adipose tissues compared to visceral adipose tissues, which is strongly correlated with BMI and insulin resistance, while Twist2 is more ubiquitously expressed in the body." (PMID 34660572, 2021).
melanoma (2 papers, 2022 to 2024). A malignant, usually aggressive tumor composed of atypical, neoplastic melanocytes. "Ectopic WT-Bmal1 and dHLH-Bmal1 increased genes associated with mesenchymal melanoma state, such as Sox9, Fn1, Col1a1, Prrx2, Klf4, Snai2, Twist2, Lmo1 and Axl31." (PMID 38245503, 2024).
non-small cell lung carcinoma (2 papers, 2025). A group of at least three distinct histological types of lung cancer, including non-small cell squamous cell carcinoma, adenocarcinoma, and large cell carcinoma. "The downregulation of miR-22-5p is known to contribute to the malignant progression of non-small-cell lung cancer by targeting TWIST2 (twist family BHLH transcription factor 2)." (PMID 40075907, 2025).
ovarian tumors (2 papers, 2013). "IHC analyses indicated the presence of high levels of Twist2 in cancer cells of primary ovarian tumors on tissue array." (PMID 24244294, 2013). "The immunostaining analyses indicated the presence of high levels of Twist2 and HIF-1α in the areas containing the cancer cells of the primary ovarian tumors." (PMID 23946798, 2013).
pulmonary fibrosis (2 papers, 2020 to 2023). Chronic progressive interstitial lung disorder characterized by the replacement of the lung tissue by connective tissue, leading to progressive dyspnea, respiratory failure, or right heart failure. "We next addressed how the expression of EMT-inducing transcription factors, Snai1, Snai2, Twist1, Twist2, Zeb1 and Zeb2, changed in the lungs from WT and Plaur-/- mice at Day 7, 14, 21 and 28 after bleomycin-induced pulmonary fibrosis." (PMID 36674896, 2023).
renal carcinoma (2 papers, 2024 to 2025). A carcinoma arising from the epithelium of the renal parenchyma or the renal pelvis. "have shown that Twist2 is involved in the progression of renal cancer by regulating ITGA6 and CD44 in the ECM-receptor interaction pathway." (PMID 39944833, 2025). "Twist2 may promote the migration and invasion of renal cancer cells by regulating the expression of ITGA6 and CD44." (PMID 38254353, 2024).
acute myeloid leukemia (1 paper, 2017). Acute myeloid leukemia (AML) is a group of neoplasms arising from precursor cells committed to the myeloid cell-line differentiation. "(2015), showing that in acute myeloid leukemia (AML) in around 30% of examined cases hypermethylation of TWIST2 occurred leading to reduced expression of both TWIST2 and the cyclin‐dependent kinase inhibitor p21." (PMID 28556516, 2017).
Brachycephaly (1 paper, 2016). An abnormality of skull shape characterized by a decreased anterior-posterior diameter. "All Hand2CAT/+; Twist2-Cre (hereafter Hand2BP) mice died neonatally with severe craniofacial defects, including brachycephaly, eyelid colobomas, and small pinna, which were similar to the defects observed in the Hand2NC mutants." (PMID 27329940, 2016).
brain arteriovenous malformations (1 paper, 2023). "Finally, SCENIC analysis identified TWIST2, MTA3, and SMAP2 as possible key EndMT EC differentiation-regulating TFs, among which TWIST2 has been confirmed as the key TF in EndMT ECs in brain arteriovenous malformations." (PMID 37853464, 2023).
Clear cell carcinomas (1 paper, 2013). "According to histological type classification, strong expression of Twist2 was found in 19 of 69 serous carcinomas (27.54%), 1 of 8 mucinous carcinomas (12.5%), none of 4 endometriod carcinomas (0%), and 2 of 5 Clear cell carcinomas (40%)." (PMID 24244294, 2013).
ductal breast carcinomas (1 paper, 2012). "Twist2 increased significantly with tumor metastasis, especially in cytoplasm of ductal carcinoma of breast cells." (PMID 23133563, 2012). "Presence of Twist2 in the nucleus only also correlated with tumor histological type, mainly in lobular carcinomas of breast (8/22, 36.36%) relative to ductal carcinomas (8/115, 6.96%)." (PMID 23133563, 2012). "Additionally, cytoplasm Twist2 expression was mainly in ductal carcinoma of breast relative to lobular carcinoma (39.13% vs. 9.09%)." (PMID 23133563, 2012). "Interestingly, presence of Twist2 in the cytoplasm only correlated with tumor histological type, mainly in ductal carcinomas of breast (45/115, 39.13%) relative to lobular carcinomas (2/22, 9.09%)." (PMID 23133563, 2012).
dwarfism (1 paper, 2016). "To further demonstrate that Evc2 loss of function in the perichondrium is critically involved in the elevation of FGF signaling and pathogenesis of dwarfism, we used the Dermo1(Twist2)Cre allele that demonstrates recombination in both chondrocytes and the perichondrium." (PMID 28027321, 2016).
Glomerular sclerosis (1 paper, 2022). Accumulation of scar tissue within the glomerulus. "Importantly, we identified a pathological transcription factor, Twist2, which might mediate the FSGS-dependent increase in glomerular sclerosis; additionally, we showed that a reduction in Twist2 expression by NMN is a potential intervention that can attenuate progressive FSGS." (PMID 35962139, 2022). "The inactivation of Twist2 by an endogenous ligand or exogenous substance like NMN might regulate the expression of Nmnat1 and reduce glomerular sclerosis due to PARP1 suppression." (PMID 35962139, 2022).
invasive ductal breast carcinoma (1 paper, 2012). The most common type of invasive breast carcinoma, accounting for approximately 70% of breast carcinomas. "Our study showed that, in some cases of invasive ductal breast carcinoma, Twist2 were mainly localized in cytoplasm of cancer cells expressing E-cadherin at tumor center and the lymph metastases." (PMID 23133563, 2012).
keloid (1 paper, 2021). An irregularly shaped, elevated mark on the skin caused by deposits of excessive amounts of collagen during wound healing. "Moreover, TWIST1, an important paralog of TWIST2, was involved in the fibrogenesis of keloid fibroblasts, and might serve as a therapeutic target of keloid, suggesting that TWIST2 might also be considered as a promising therapeutic target in HS." (PMID 35047019, 2021).
lung adenocarcinoma (1 paper, 2025). A carcinoma that arises from the lung and is characterized by the presence of malignant glandular epithelial cells. "PIK3C2B expression showed significant positive correlations with key EMT regulators: SNAI1 (r = 0.11, p = 0.00098), VIM (r = 0.21, p = 1e-10), ZEB1 (r = 0.37, p = 6.7e-33), and TWIST2 (r = 0.11, p = 0.00034) in TCGA lung adenocarcinoma samples." (PMID 41362647, 2025).
malignant glioma (1 paper, 2016). A grade III or grade IV glioma arising from the central nervous system. "The current research has shown EMT-like changes in malignant gliomas, including a role for SNAIL1/SNAIL2, TWIST1/ TWIST2, ZEB1/ZEB2 and miRNAs as inducers for a cell-invasive phenotype in GBMs." (PMID 26761212, 2016).
metastatic tumors (1 paper, 2022). "Note that expression of SNAIL2, ZEB1, ZEB2, TWIST2 was significantly lower in the distant metastatic tumors (Met_distant, n = 628) than other subgroups." (PMID 35272617, 2022).
Nephropathy (1 paper, 2016). A nonspecific term referring to disease or damage of the kidneys. "To test the role for quercetin in ameliorating tubular cell EMT in the kidneys with UUO nephropathy, we detected the mRNA expression for Twist1, Twist2, Snail1 and Snail2 in the kidneys at 2 weeks after UUO surgery." (PMID 27052477, 2016).
nonalcoholic steatohepatitis (1 paper, 2021). "The present study focuses on the role of TWIST1, TWIST2 and PPARγ in nonalcoholic steatohepatitis progression." (PMID 33879188, 2021).
osteoporosis (1 paper, 2021). A condition of reduced bone mass, with decreased cortical thickness and a decrease in the number and size of the trabeculae of cancellous bone (but normal chemical composition), resulting in increased fracture incidence. "However, both Twist2-Cre and Col1α1-Cre Runx1 mutant CKO mice displayed a severe osteoporosis phenotype, while a more severe osteoporosis phenotype was observed in 8-month-old mutant mice." (PMID 33476325, 2021). "However, in this study, our results demonstrated that Runx1 conditional knockout mice using Twist2-Cre and Col1α1-Cre (Runx1 CKO) displayed a severe osteoporosis phenotype." (PMID 33476325, 2021).
papillary thyroid carcinomas (1 paper, 2017). "By studying the gene expression changes induced by BRAFV600E, we found enrichment of TGF-β/EMT signatures and a correlation with TWIST2 expression in human papillary thyroid carcinomas." (PMID 28350298, 2017).
pharynx cancer (1 paper, 2011). A primary or metastatic malignant neoplasm that affects the pharynx. "We found that high expression levels of TWIST2 significantly correlated with shorter survival in oral cavity/pharynx cancer patients, even after adjustment for tumor grading." (PMID 22201613, 2011). "More importantly, we demonstrate that TWIST2 correlates with high tumor grade and short survival in oral cavity/pharynx cancer patients and identifies, within the N-positive category, a subset with high risk of progression." (PMID 22201613, 2011). "Thus, TWIST2 expression identifies a group of node-positive oral cavity/pharynx cancer patients highly prone to progression." (PMID 22201613, 2011).
pharynx tumors (1 paper, 2011). "Rather, our study suggests that the assessment of TWIST2 expression, particularly in node-positive oral cavity/pharynx tumors, might help in identifying those cases that are at higher risk of fatal progression, pointing to TWIST2 as a potential marker." (PMID 22201613, 2011).
renal fibrosis (1 paper, 2017). A final common manifestation of a wide variety of chronic kidney diseases characterized by glomerulosclerosis and tubulointerstitial fibrosis. "To begin to elucidate mechanism(s) underlying dysrepair in the aging kidney, we examined the expression of Twist2, a helix-loop-helix transcription factor that may mediate renal fibrosis." (PMID 28208580, 2017).
rhabdomyosarcoma (1 paper, 2021). A rare aggressive malignant mesenchymal neoplasm arising from skeletal muscle. "Knockdownof TWIST2 in Rhabdomyosarcoma cells resulted in up-regulation of MyoD and MyoGas well as a decrease in proliferation." (PMID 33554216, 2021).
Sezary syndrome (1 paper, 2023). Sezary syndrome (SS) is an aggressive form of cutaneous T-cell lymphoma characterized by a triad of erythroderma, lymphadenopathy and circulating atypical lymphocytes (Sezary cells). "Similarly to TWIST1, TWIST2 was also found to be expressed highly in a Sezary syndrome (CTCL) cell line compared to a T-ALL cell line in one study, however no further evidence to support a role for TWIST2 in this disease has been published to date." (PMID 37600794, 2023).
steatosis (1 paper, 2021). Increased lipid within the cytoplasm of cells. "The present study will continue previous work to explore the role and possible mechanism of TWIST1, TWIST2, and PPARγ in the development of hepatocyte steatosis." (PMID 33879188, 2021). "The results provide evidence that the TWIST2 and PPAR signaling pathways are important in NAFLD and shed light on a potential mechanism of steatosis." (PMID 33879188, 2021). "In summary, the present study shows that the TWIST2 and PPAR signaling pathways are important in NAFLD and sheds light on a potential mechanism of steatosis." (PMID 33879188, 2021).
tongue squamous cell carcinoma (1 paper, 2013). A squamous cell carcinoma that arises from the tongue. "The same expression pattern of HIF-1α and Twist2 is also observed in tongue squamous cell carcinoma where it is associated with a shorter disease-free survival." (PMID 23946798, 2013).
tumor (66 papers, 2010 to 2026). "In contrast, TWIST2 functions as a tumor suppressor, and its loss is correlated with a higher malignancy potential." (PMID 39941895, 2025). "Prior studies have linked TWIST1 and the related protein TWIST2 to drug resistance in multiple tumour types, including ovarian, but the specific mechanism by which TWIST1 drives resistance in EOC is not well understood." (PMID 27876874, 2016). "But the nuclear Twist2 positive cells surrounding the lymph metastases showed loss of E-cadherin at the tumor invasion fronts." (PMID 23133563, 2012). "Though further studies are warranted, Twist2 may be playing a role in causing ESCC tumor cells to undergo EMT and become more invasive." (PMID 33139779, 2020). "Expression of Twist1 and Twist2 in human solid tumors has been associated with tumor progression." (PMID 31921617, 2019). "However,TWIST2 levels were significantly associated with tumor grade (p <0.0001) with the lowest levels in Grade III." (PMID 29156759, 2017). "The differential cellular distribution of Twist2 may be associated with its role in tumor progression." (PMID 23133563, 2012). "The differential cellular distribution of Twist2 may be associated with tumor progression." (PMID 23133563, 2012). "A functional study demonstrated that TWIST2 OE in LNCap cells reduced cell proliferation and tumor growth in mouse xenograft models." (PMID 41008642, 2025). "Gene annotation and pathway analysis on the unique identified H3K4me3 peaks from KO tumours corroborated these findings by showing enrichment of Twist1, Twist2 and extracellular matrix organization." (PMID 36933062, 2023). "For instance, AKR1B1 transcription is enhanced by Twist2, a well characterized promoter of epithelial–mesenchymal transition that cooperates with tumor aggressiveness." (PMID 37780210, 2023). "miR-22-5p upregulation or TWIST2 downregulation substantially decreased the tumor proliferation ability of NSCLC cells, whereas TWIST2 upregulation remarkably restored the proliferation ability damaged by miR-22-5p." (PMID 36111260, 2022). "And the Twist2 protein levels were obviously increased in HCC tumor tissues, which were negatively related to miR-1236-3p, while it was positively related to circ_0067835." (PMID 36262967, 2022). "Galván and colleagues first showed that TWIST1 and TWIST2 protein expression are found nearly exclusively in the tumor stroma." (PMID 34768901, 2021). "Evidence from the tumor stroma points to epigenetic changes favoring the budding process, for example, methylation of TWIST1 and TWIST2 in stromal cells, or changes in miRNA has been found to occur in non-tumor budding regions." (PMID 33843013, 2021). "TWIST2, is a transcription factor that modulates tumor invasion and migration through EMT, but its regulatory mechanism in GC is unclear." (PMID 33206629, 2020). "Re-introduced Twist2 gene expression in an ALL cell line inhibited tumor growth and induced apoptosis to cytotoxic agents." (PMID 29685144, 2018). "Promoter methylation of TWIST2 was found in more than half of the cases and restoration of TWIST2 expression resulted in growth inhibition and apoptosis in vitro suggestive of tumor‐suppressive functions." (PMID 28556516, 2017). "Our networks showed a group of conserved associations between the miR-200 networks inferred from tumour and control data, this association core is conformed by miR-200 miRs and known transcription factors such as: TWIST-1, TWIST-2, ZEB-1 and ZEB-2." (PMID 29051564, 2017). "Multivariate analysis demonstrated that vascular endothelial growth factor (VEGF) (P = 0.002), epidermal growth factor receptor (EGFR) (P = 0.001), and TWIST2 (P = 0.001) expression levels, as well as a tumor size <6 cm (P = 0.02), influenced OS." (PMID 27230280, 2016).